DHODH (dihydroorotate dehydrogenase (quinone))
Diseases named in the same sentence as DHODH in open-access papers (continued):
Sharing a sentence is not in itself a finding about the gene and the disease.
autoimmune disease (16 papers, 2016 to 2025). A disorder resulting from loss of function or tissue destruction of an organ or multiple organs, arising from humoral or cellular immune responses of the individual to their own tissue constituents. "Our results are in line with a beneficial effect of DHODH inhibitors in other autoimmune diseases, such as MS, Lupus and colitis." (PMID 40706797, 2025). "DHODH inhibitors are used in the treatment of autoimmune diseases and are currently under investigation for their antiviral and anticancer potencies." (PMID 36814599, 2023). "Dihydroorotate dehydrogenase (DHODH) is a central enzyme of the de novo pyrimidine biosynthesis pathway and is a promising drug target for the treatment of cancer and autoimmune diseases." (PMID 37744270, 2023). "A number of DHODH inhibitors have become available for clinical testing or were even approved for therapy, mostly to treat autoimmune diseases, due to their selective inhibition of hyperactive immune cells." (PMID 35492218, 2022). "Considering the crucial role of DHODH in rapidly proliferating cells (like lymphocytes), pharmacological targeting DHODH has revealed ideal effect in inflammatory disease, and autoimmune disease." (PMID 34123854, 2021). "Dihydroorotate dehydrogenase (DHODH) is essential for the de novo synthesis of pyrimidine ribonucleotides, and as such, its inhibitors have been long used to treat autoimmune diseases and are in clinical trials for cancer and viral infections." (PMID 34113829, 2021). "Previous studies extensively explored DHODH as a potential drug target across autoimmune diseases, oncology, and infectious diseases." (PMID 31047779, 2019). "Likewise, DHODH inhibition by IMU-838 or Vidofludimus free acid improved disease outcomes in preclinical models of autoimmune diseases such as colitis and experimental autoimmune encephalomyelitis (EAE)." (PMID 40706797, 2025). "In particular, DHODH inhibitors are applied in autoimmune disorders and may be beneficial for the treatment of viral diseases including SARS‐CoV‐2." (PMID 36134475, 2022). "For this reason, DHODH inhibitors have been developed for treating cancer and autoimmune diseases." (PMID 34578395, 2021). "Components of the de novo pyrimidine biosynthesis pathway, and DHODH in particular, are becoming drug targets of prime interest in the treatment of multiple pathologies, including viral and microbial infections, cancer, and autoimmune diseases." (PMID 28807907, 2017). "Interestingly, the inhibitors of DHODH are currently used for the therapy of autoimmune diseases, and celastrol has long been proved to be very effective for this kind of disease." (PMID 27374097, 2016). "Additionally, DHODH suppression might exert anti-inflammatory activities in autoimmune disease treatment by preventing the generation of proinflammatory Th1 effectors and promoting Th2 cell differentiation." (PMID 33971967, 2021). "ASLAN003, a DHODH inhibitor developed by ASLAN Pharmaceuticals (Singapore, SG), was initial designed for the treatment of autoimmune disease." (PMID 34123854, 2021). "However, because GDF15 can protect the pancreas from inflammation at least in type 1 diabetes, and because DHODH inhibitors are used against autoimmune diseases, it is still possible that to some extent, DHODH inhibitors could protect the pancreas from inflammation." (PMID 34113829, 2021). "Human dihydroorotate dehydrogenase (DHODH), the enzyme that catalyzes the rate‐limiting step in de novo pyrimidine biosynthesis, is considered to be an attractive target for potential treatment of autoimmune disease and cancer." (PMID 31087527, 2019).
breast carcinoma (15 papers, 2017 to 2025). "Because of its unique localization and pleiotropic roles, DHODH is frequently upregulated in malignancies, including colorectal cancer, hepatocellular carcinoma, glioblastoma, breast cancer, and renal cell carcinoma." (PMID 41369379, 2025). "In breast cancers, nanoparticles carrying DHODH inhibitors enhanced lipid peroxidation and ferroptosis with no significant adverse effects." (PMID 41369379, 2025). "The CoQ-dependent DHODH seems to also be important in tumorigenesis since the pyrimidine biosynthesis required in mouse breast cancer cells need a functional CoQ redox-cycling and DHODH activity." (PMID 33810539, 2021). "It reminds us of distinguishing the sensitivity of breast cancer cells to DHODH inhibitor by considering different molecular mechanism and DHODH inhibition as an alternative method for breast cancer treatment." (PMID 33971967, 2021). "DHODH is overexpressed in human breast cancer tissues, and breast cancer cells expressing high DHODH show high sensitivity to DHODH inhibitors." (PMID 33971967, 2021). "Leflunomide induces S phase arrest and accumulation of cyclin E in breast cancer cells, which is further supported in DHODH-silenced cells." (PMID 33971967, 2021). "PTEN-mutant human breast cancer cell lines display increased cell death overtime upon treatment with DHODH inhibitor leflunomide." (PMID 33971967, 2021). "Meanwhile, there is also a study that finds DHODH inhibitor-sensitive breast cancer cells reveal unchanged ROS production." (PMID 33971967, 2021). "For example, DHODH inhibition affects ATP depletion in breast cancer cells." (PMID 33971967, 2021). "DHODH suppression by leflunomide decreased cell motility in breast cancer cells, which could explain the anti-metastatic effect of leflunomide." (PMID 33971967, 2021). "In breast cancer, the deubiquitinase USP24 stabilizes DHODH protein, protecting tumor cells from ferroptosis by preventing DHODH degradation." (PMID 41369379, 2025). "Similarly, dual inhibition of DHODH and FSP1 has shown promising results in colorectal and breast cancer models, as both enzymes converge on ubiquinol regeneration pathways." (PMID 41369379, 2025). "Several clinical trials are currently evaluating DHODH inhibitors as anti-cancers and will elucidate whether DHODH is a specific vulnerability of CRC, NSCLC and breast cancer." (PMID 35912247, 2022). "The overexpression of DHODH are observed in multiple malignance cells, including AML, skin cancer, colorectal cancer (CRC), pancreatic cancer, breast cancer, lung cancer, multiple myeloma cells, neuroblastoma cells, renal cell carcinoma (RCC), cervical cancer, and glioblastoma stem cells (GSCs)." (PMID 33971967, 2021). "DHODH suppression induces sensitivity to TRAIL and replication stress in MCF-7 breast cancer cells." (PMID 33971967, 2021). "We also found some support for an association between breast cancer risk and eQTL for ACAP1 (EUGENE P = 0.003) and ANKLE1 (EUGENE P = 0.01), but not for DHODH (best sentinel eQTL P = 0.119)." (PMID 30988301, 2019).
breast carcinoma (continued). "For overall breast cancer risk, there was no gene with a P-value that deviated from the null distribution, but for ER-negative breast cancer risk analysis, there were several genes with P-values smaller than expected, including TP53INP2, HP, and DHODH." (PMID 28957356, 2017).
neuroblastoma (12 papers, 2013 to 2025). Neuroblastoma (NB) is the most common solid, extracranial childhood tumor. "Further research in these areas will provide deeper insights into the mechanisms underlying DHODH inhibition and its potential therapeutic applications in neuroblastoma." (PMID 40513779, 2025). "We then performed docking simulations to identify and evaluate potential FDA-approved drugs capable of inhibiting DHODH activity in high-risk neuroblastoma, confirming their efficacy through both cell-based assays and patient-derived organoid models." (PMID 40513779, 2025). "Abnormalities in pyrimidine metabolism, which are closely linked to uncontrolled cell proliferation, make DHODH a key contributor to cancer development, particularly in high-risk neuroblastoma, where it is associated with MYCN status." (PMID 40513779, 2025). "In neuroblastoma, DHODH expression was identified as an independent risk factor for aggressive disease, and high DHODH levels correlated to worse overall and event-free survival." (PMID 35943801, 2022). "Notably, DHODH is an independent risk factor for neuroblastoma, and high DHODH expression is significantly associated with a poor prognosis." (PMID 38796629, 2024). "Targeting DHODH as a cancer-specific metabolic dependency may benefit high-risk neuroblastoma patients and is a strong candidate for further testing in clinical studies." (PMID 35943801, 2022). "Interestingly, the highest levels of DHODH expression were observed in high-risk, MYCN-amplified tumors, and DHODH expression increased with International Neuroblastoma Staging System (INSS) stage." (PMID 35943801, 2022). "Given DHODH’s pivotal role in neuroblastoma, identifying effective DHODH-targeting drugs for this disease is of high priority." (PMID 40513779, 2025). "Based on these screening and evaluation results, Regorafenib stands out as a promising therapeutic candidate for neuroblastoma, showing potent DHODH inhibition and significant reduction in cell viability." (PMID 40513779, 2025). "This suggests that Regorafenib influences the production of neutral lipids by inhibiting DHODH, which subsequently reduces lipid droplet formation in neuroblastoma cells and promotes ferroptosis." (PMID 40513779, 2025). "To investigate how Regorafenib-mediated DHODH inhibition affects neuroblastoma cells, we conducted TMT-based quantitative proteomics analysis using TMT labeling and LC/MS-MS." (PMID 40513779, 2025). "We first examined the DHODH expression levels in five neuroblastoma cell lines available in our laboratory." (PMID 40513779, 2025). "In summary, our study highlights DHODH blockade as a novel approach to induce ferroptosis through lipid metabolism reprogramming, underscoring DHODH as a viable therapeutic target for neuroblastoma treatment." (PMID 40513779, 2025). "In this study, we utilized clinical data and silencing cell-based experiments to establish that DHODH is a potential therapeutic target for neuroblastoma." (PMID 40513779, 2025). "To gain deeper insights into the molecular mechanisms by which DHODH inhibition impacts neuroblastoma, we conducted Tandem Mass Tag (TMT) proteomic analysis to profile proteome changes following DHODH inhibition." (PMID 40513779, 2025). "In contrast, our findings reveal a novel mechanism whereby DHODH inhibition disrupts lipid metabolism and promotes ferroptosis in neuroblastoma." (PMID 40513779, 2025). "This research not only presents a promising therapeutic avenue for neuroblastoma but also reveals a novel role of DHODH as a key regulator of ferroptosis." (PMID 40513779, 2025). "We initially used confocal microscopy (63× magnification) to assess lipid droplet formation in neuroblastoma cells treated with Regorafenib or subjected to DHODH knockdown." (PMID 40513779, 2025). "We identified that FDA-approved drug Regorafenib induces ferroptosis in neuroblastoma cells by inhibiting DHODH." (PMID 40513779, 2025).
neuroblastoma (continued). "Preclinical studies on pharmacologic DHODH inhibition have shown efficacy against neuroblastoma and medulloblastoma, which are also pediatric cancers." (PMID 38332874, 2024). "Within the publicly available CCLE dataset, DHODH was expressed at higher levels in MB, neuroblastoma, and rhabdoid tumour cell lines when compared to other paediatric cancer cell lines." (PMID 39766063, 2024). "This indicated a potential biological role of DHODH in neuroblastoma and prompted us to perform further analyses to evaluate DHODH as a therapeutic target." (PMID 35943801, 2022). "In conclusion, our data demonstrate the therapeutic impact of DHODH as a critical mediator of neuroblastoma cell growth." (PMID 35943801, 2022). "Specific DHODH inhibition combined with the alkylating agent temozolomide is highly effective in neuroblastoma preclinical models." (PMID 35943801, 2022). "The aim of this study was to identify metabolic vulnerabilities in neuroblastoma and to evaluate the role of DHODH as a potential therapeutic target in this disease." (PMID 35943801, 2022). "DHODH was identified to be an effective target in MYCN-amplified neuroblastoma cell lines and mouse neuroblastoma models." (PMID 35203388, 2022). "A combination of DHODH inhibition and temozolomide demonstrates curative potential in transgenic neuroblastoma mice." (PMID 35943801, 2022). "In this study we applied a pancancer, multiomic approach to elucidate metabolic dependencies in cancer and identified critical roles of DHODH, both as a prognostic marker and as a mediator of tumor cell survival in neuroblastoma." (PMID 35943801, 2022). "Overall, DHODH inhibition combined with temozolomide has therapeutic potential in neuroblastoma, and we propose this combination for clinical testing." (PMID 35943801, 2022). "In comparison with other solid tumor cell lines and primary pediatric tumor samples, DHODH was expressed at high levels in neuroblastoma and rhabdoid tumors." (PMID 35943801, 2022). "We report that the therapeutic combination of DHODH inhibition and the standard-of-care chemotherapeutic temozolomide has curative potential in a transgenic neuroblastoma mouse model and may be a promising candidate for the treatment of high-risk neuroblastoma." (PMID 35943801, 2022). "Taken together, high DHODH expression is significantly correlated with adverse outcomes in patients with neuroblastoma." (PMID 35943801, 2022). "We next evaluated 2 independent cohorts to investigate the prognostic implications of DHODH expression in human neuroblastoma." (PMID 35943801, 2022). "In xenograft and transgenic neuroblastoma mouse models treated with the DHODH inhibitor brequinar, tumor growth was dramatically reduced, and survival was extended." (PMID 35943801, 2022). "By analyzing publicly available, large neuroblastoma patient cohorts, we presented DHODH expression as an independent prognostic marker in neuroblastoma after adjusting for known adverse factors, such as disease stage, age, and MYCN amplification." (PMID 35943801, 2022). "DHODH inhibition can inhibit a variety of cancer cells, including multiple myeloma cells, neuroblastoma cells, RCC, cervical cancer, and GSCs." (PMID 33971967, 2021). "As a rate-limiting enzyme of nucleotide metabolism pathway, DHODH seemed to contribute to malignant characteristics of various tumors, including multiple myeloma, chronic lymphocytic leukemia, neuroblastoma, colon cancer, prostate cancer, and so on." (PMID 29348830, 2017). "Our study revealed that leflunomide inhibited cell proliferation and tumor growth through down-regulation DHODH pathway in neuroblastoma cells." (PMID 23977077, 2013). "We found that DHODH was commonly expressed in BE-2C, SK-N-DZ, and SK-N-F1 all three neuroblastoma cell lines." (PMID 23977077, 2013). "Leflunomide treatment in neuroblastoma showed a great inhibition of DHODH expression and tumor growth when administered in clinically reasonable concentrations." (PMID 23977077, 2013).